EHMT2 (euchromatic histone lysine methyltransferase 2)
Diseases named in the same sentence as EHMT2 in open-access papers (continued):
Sharing a sentence is not in itself a finding about the gene and the disease.
lung adenocarcinoma (10 papers, 2017 to 2023). A carcinoma that arises from the lung and is characterized by the presence of malignant glandular epithelial cells. "(I) Spearman’s rank correlation analysis between orthogonal human AT2 gene signatures and EHMT2 transcript in 546 human lung adenocarcinomas (LUAD)." (PMID 35983994, 2022). "Consequently, EHMT2 inhibition prevents KrasG12D lung adenocarcinoma (LUAD) tumor formation and propagation and disrupts normal AT2 cell differentiation." (PMID 35983994, 2022). "It was previously demonstrated that HP1γ functions as a coactivator of GR after its recruitment through the histone lysine methyltransferases G9a and GLP (EHMT2 and EHMT1, respectively) in lung adenocarcinoma and B-cell acute lymphoblastic leukemia." (PMID 37536978, 2023).
Obesity (10 papers, 2016 to 2025). Accumulation of substantial excess body fat. "In the MVMR analysis, the reduced risk of osteoporosis caused by obesity-related indicators may be mediated by EHMT2 among plasma proteins and alanine among blood metabolites." (PMID 40041284, 2025). "Numerous enzymes associated with H3K9me3, the mark associated with heterochromatin, including acetyltransferases (SRC‐1/Ncoa1), deacetylases (Hdac3), methyltransferases (Suv39 h1 and G9a/Ehmt2), and demethylases (Jhmdh2a/Kdm3a, Jmjd2c/Kdm4c), have been linked to fatty liver, diabetes, and obesity." (PMID 29484800, 2018). "Hence, we sought to testify if there is a relationship between miR-205-5p and EHMT2 in the pathophysiological processes of obesity-induced atrial fibrosis and to investigate whether EHMT2-induced H3K9 or H3K4 modification underlies the dysregulated expression of genes related to AF." (PMID 35858845, 2022). "By affecting the expression of these pleiotropic genes, EHMT2 may indirectly influence the onset of obesity and osteoporosis." (PMID 40041284, 2025). "The findings of this study suggest that obesity may have a certain protective effect against osteoporosis, potentially mediated by EHMT2 in plasma proteins and alanine in blood metabolites." (PMID 40041284, 2025). "Further MVMR and mediating MR found that the plasma protein EHMT2 and blood metabolite alanine may mediate the effects of obesity-related indicators, specifically waist circumference, on osteoporosis." (PMID 40041284, 2025). "This suggests that obesity may exert a protective effect on osteoporosis through the mediation of EHMT2 and alanine." (PMID 40041284, 2025). "Obesity may confer a protective effect against osteoporosis, potentially mediated by EHMT2 in plasma proteins and alanine in blood metabolites." (PMID 40041284, 2025). "Moreover, EHMT2 can mediate HFD-induced obesity, hepatic steatosis, and hepatic insulin resistance, emerging as a therapeutic candidate for obesity and associated diseases." (PMID 35858845, 2022).
prostate carcinoma (9 papers, 2015 to 2025). A carcinoma that arises from epithelial cells of the prostate gland. "Recent studies have implicated EHMT1 and EHMT2 as critical epigenetic drivers in prostate cancer." (PMID 37663929, 2023). "EHMT2 knockout inhibits the proliferation of prostate cancer cells and induces apoptosis in prostate cancer cells." (PMID 39465737, 2024). "Through comprehensive investigations, we discovered that both EHMT1 and EHMT2 proteins have the ability to activate oncogenic transcription programs in prostate cancer cells." (PMID 37663929, 2023). "Overall, these studies suggest a strong therapeutic potential for using dual inhibitors of EHMT1 and EHMT2 for treating prostate cancer." (PMID 37663929, 2023). "To determine the role of EHMT1 and EHMT2 in prostate cancer progression, we examined their protein levels in adenocarcinoma prostate cancer lines (LNCaP, 22Rv1) and stem cell or neuroendocrine (NE)-like prostate cancer lines (PC-3, NCI-H660)." (PMID 37663929, 2023). "In this study, we demonstrate that EHMT1 and EHMT2 proteins drive prostate cancer development by transcriptionally activating multiple oncogenic pathways." (PMID 37663929, 2023). "In addition, a recently published study reveals the oncogenic function of EHMT2 in mediating the function of the PRC2 (polycomb repressive complexes 2) complex in prostate cancer cells." (PMID 37663929, 2023). "The growth of these prostate cancer cells was reduced upon knockdown of either EHMT1 or EHMT2." (PMID 37663929, 2023). "Silencing EHMT1 or EHMT2 effectively suppresses prostate cancer cell proliferation and migration." (PMID 37663929, 2023). "However, the specific function and regulation of EHMT1 (also known as GLP) and EHMT2 (also known as G9A), well-known histone 3 lysine 9 methyltransferases, in prostate cancer progression remain poorly understood." (PMID 37663929, 2023). "We also demonstrate the statistically significant down-regulation of DNA methyltransferases (COMT, MGMT, EHMT2, and SIRT1 deacetylase) in saffron-treated prostate cancer cells." (PMID 38201944, 2023). "Interestingly, a previous study reported that EHMT2 can methylate lysine 114 of LSD1, leading to its recognition and interaction with the chromatin-remodeling protein CHD1 to activate gene transcription in prostate cancer cells." (PMID 37663929, 2023).
non-small cell lung carcinoma (8 papers, 2020 to 2026). A group of at least three distinct histological types of lung cancer, including non-small cell squamous cell carcinoma, adenocarcinoma, and large cell carcinoma. "Eukaryotic histone methyltransferases 2 (EHMT2 or G9A) has been regarded as a potential target for non-small cell lung cancer (NSCLC) therapy." (PMID 32552834, 2020).
Cognitive impairment (7 papers, 2021 to 2025). Abnormal cognition is characterized by deficits in thinking, reasoning, or remembering. "Given the elevation of EHMT2, we next tested whether EHMT inhibition could alleviate cognitive deficits in P301S Tau mice (5–7 months old)." (PMID 34547169, 2021).
Insulin resistance (7 papers, 2018 to 2025). Increased resistance towards insulin, that is, diminished effectiveness of insulin in reducing blood glucose levels. "We first reduced the expression of EHMT2 in mouse liver and found that this worsened GC-induced insulin resistance whereas hypertriglyceridemia and hepatic steatosis induced by GC were not affected." (PMID 37253782, 2023). "If Dex-induced insulin resistance is improved because of EHMT2 being specifically expressed in the liver, this would validate the key role of hepatic EHMT2’s coactivation function in the phenotypes we observed." (PMID 37253782, 2023). "Overall, reducing EHMT2 expression in mouse liver exacerbated Dex-induced insulin resistance." (PMID 37253782, 2023). "Overall, we propose a model in which glucocorticoid-regulated insulin sensitivity is determined by the balance between glucocorticoid-modulated insulin resistance and insulin sensitizing genes, in which EHMT2 coactivation is specifically involved in the latter process." (PMID 37253782, 2023). "Reducing EHMT2 expression compromises both the coactivator and corepressor functions and thus does not distinguish which is responsible for the exacerbated Dex-induced insulin resistance observed above." (PMID 37253782, 2023). "Thus, overexpression of EHMT2 prevents palmitic acid- or glucosamine-induced insulin resistance by preserving normal insulin signaling." (PMID 37253782, 2023). "Furthermore, recent studies addressed the mechanisms linking the downregulation of the histone methyltransferase G9a/EHMT2 with insulin resistance in murine models and in cultured human hepatic cells." (PMID 30034366, 2018). "To test whether the exacerbated GC-induced insulin resistance observed in Ehmt2K182R/K182R mice is due to EHMT2’s function in the liver, we infected Ehmt2K182R/K182R mice with adeno-associated virus serotype 8 (AAV8) expressing GFP (AAV8-GFP) or human EHMT2 (AAV8-hEHMT2)." (PMID 37253782, 2023). "In the case of IRS1 (cg21511036), AKT1S1 (cg03813033), ADCY2 (cg12566890 and EHMT2 (cg00210002) are hypomethylated, whereas AKT1 (cg01749142), FOXO3 (15283498), are hypermethylated in subjects with insulin resistance and hypertriglyceridemia." (PMID 30926763, 2019).
Kleefstra syndrome (7 papers, 2017 to 2024). A genetic disorder characterized by intellectual disability, childhood hypotonia, severe expressive speech delay and a distinctive facial appearance with a spectrum of additional clinical features. "The functions of EHMT1 and EHMT2 have been implicated in neurodevelopmental disorders, including Kleefstra syndrome and Prader-Willi syndrome, and EHMT1 has been identified as a schizophrenia susceptibility gene." (PMID 38472451, 2024). "Six other genes potentially involved in ID were included, namely ASCC3 found mutated in a single family by performing a large-scale genomic study, EHMT2 homologous to EHMT1 causing Kleefstra syndrome, and CDK8." (PMID 36551904, 2022). "Since LoF variants in EHMT1 give rise to Kleefstra syndrome, it is tempting to speculate that EHMT2 is a candidate for syndromic ID as well." (PMID 36551904, 2022).
cholangiocarcinoma (6 papers, 2021 to 2025). A carcinoma that arises from the intrahepatic biliary tree (intrahepatic cholangiocarcinoma) or from the junction, or adjacent to the junction, of the right and left hepatic ducts (hilar cholangiocarcinoma). "Recently, Ma and co-workers presented evidence that the histone-lysine methyltransferase EHMT2 is up-regulated in human cholangiocarcinoma, which enhances cell growth and invasiveness by epigenetically silencing the Hippo pathway kinase large tumor suppressor 2 (LATS2)." (PMID 34344448, 2021).
idiopathic pulmonary fibrosis (6 papers, 2014 to 2023). Idiopathic pulmonary fibrosis (IPF) is a nonneoplastic pulmonary disease that is characterized by the formation of scar tissue within the lungs in the absence of any known cause. "Meanwhile, there were significant increases in EHMT2 expression and H3K9 methylation levels in TGF-β1-induced renal fibrosis mice and bleomycin-induced pulmonary fibrosis mice." (PMID 35858845, 2022).
renal fibrosis (6 papers, 2019 to 2025). A final common manifestation of a wide variety of chronic kidney diseases characterized by glomerulosclerosis and tubulointerstitial fibrosis. "EHMT2, also named G9a, is a euchromatic H3K9 methyltransferase that participates in the process of renal fibrosis through H3K9 modification." (PMID 35858845, 2022).
cardiac hypertrophy (5 papers, 2022 to 2025). "Conversely, Ehmt2 inhibits cell death of primary aortic vascular smooth muscle cells by suppressing autophagy, and research demonstrated miR-207 to repress Ehmt1 and Ehmt2 expression leading to cardiac hypertrophy." (PMID 39285385, 2024). "EHMT2 was found to be upregulated during the initial stages of cardiac hypertrophy." (PMID 36523510, 2022).
metastatic disease (5 papers, 2014 to 2023). "G9a/Ehmt2 levels were higher in metastatic disease compared to patients with primary or relapsed disease." (PMID 37894922, 2023). "Our data showed that metastatic tumor samples had a significantly higher expression of EHMT2/G9a than primary or recurrent tumor samples, at both the mRNA (p = 0.0008) and the protein (p = 0.0005) levels." (PMID 35354905, 2022). "In ES, higher G9a/Ehmt2 was found in metastatic disease compared to non-metastatic disease." (PMID 37894922, 2023).
rhabdomyosarcoma (5 papers, 2019 to 2025). A rare aggressive malignant mesenchymal neoplasm arising from skeletal muscle. "Pal and colleagues described a role for EHMT2-mediated suppression of Wnt signaling in Rhabdomyosarcoma through activation of DKK1." (PMID 35983994, 2022).
autism (4 papers, 2019 to 2023). Persistent deficits in social interaction and communication and interaction as well as a markedly restricted repertoire of activity and interest as well as repetitive patterns of behavior. "MEAs have been deployed to investigate gene mutations associated with monogenic forms of autism in hiPSC-neurons such as CNTN5, EHMT2, KCNQ2, ATRX, and SCN2A." (PMID 37441676, 2023). "A recent publication has shown that ASD neurons derived from autism CNTN5+/− or EHMT2+/− human iPSCs develop hyperactive neuronal networks." (PMID 31893021, 2019).
brain tumor (4 papers, 2017 to 2025). "Key alterations among KMTs in pediatric brain tumors include aberrant expression of EZH2, NSD1, SETD1A, SMYD3, MLL2 (KMT2D), and G9A (EHMT2)." (PMID 40556679, 2025).
schizophrenia (4 papers, 2014 to 2025). A major psychotic disorder characterized by abnormalities in the perception or expression of reality. "A recent study showed increased expression of the EHMT2 gene in lymphocytes and the EHMT1 gene in both postmortem parietal cortex and lymphocyte samples, from patients with schizophrenia." (PMID 25400900, 2014). "The elevated expression of EHMT2 observed in peripheral blood cells from ASD patients may support the notion of a restrictive chromatin state in ASD pathogenesis, similar to schizophrenia." (PMID 25400900, 2014). "The elevated expression of EHMT2 in the peripheral blood cells may support the notion of a restrictive chromatin state in ASD, similar to schizophrenia." (PMID 25400900, 2014).
Autoimmunity (3 papers, 2018 to 2021). The occurrence of an immune reaction against the organism's own cells or tissues. "As CTLA4 is known to be associated with T1D, alterations in EHMT2 expression and/or function owing to natural variations may as well be linked to autoimmunity." (PMID 34220961, 2021). "More specifically, we hypothesize that genetic variation in EHMT2 could impact autoimmunity in type 1 diabetes development." (PMID 34220961, 2021). "In case of T1D, another pathway might be involved: Inhibition of EHMT2 has been shown to enhance CTLA4 and FOXP3 expression in regulatory T cells, both are markers of regulatory T cell function needed to maintain tolerance and prevent autoimmunity." (PMID 34220961, 2021). "Pharmacological inhibition of G9a/EHMT2 with BIX01294 results in induction of autophagy demonstrated by increased LC3B-positive autophagic vesicles, but autoimmunity was not studied in this context." (PMID 30154791, 2018).
Hypertension (3 papers, 2016 to 2022). The presence of chronic increased pressure in the systemic arterial system. "In a longitudinal genome wide methylation study of Roux-en-Y bypass patients, the EHMT2 promoter was found to be hypomethylated in hypertension, suggesting that epigenetic regulation of EHMT2 contributes to vascular pathophysiology." (PMID 29649151, 2018). "A systematic review of the role of DNA methylation in modifying blood pressure showed that lower methylation levels of SULF1 (sulfate endosulfatase), EHMT2 (Euchromatic Histone Lysine Methyltransferase 2), and SKOR2 (SKI Family Transcriptional Corepressor 2) were associated with hypertension." (PMID 36293177, 2022). "It remains to be explored whether IL-17 has effects in human hypertension and whether epigenetic regulation of EHMT2 is alter the hypertensive state." (PMID 29649151, 2018).
liver fibrosis (3 papers, 2021 to 2025). "In liver fibrosis models, combined G9a (EHMT2) and DNMT1 inhibition reverses these epigenetic aberrations." (PMID 41155602, 2025).
triple-negative breast carcinoma (3 papers, 2015 to 2026). An invasive breast carcinoma which is negative for expression of estrogen receptor (ER), progesterone receptor (PR), and human epidermal growth factor receptor 2 (HER2). "The effects on gene expression of the selective EZH2 inhibitor GSK343 and the selective EHMT2 inhibitor UNC0638 used alone or in combination were also examined using the MDA-MB-231 triple negative breast cancer cell line." (PMID 26300989, 2015). "We report that gene expression and inhibition of triple negative breast cancer cell growth (MDA-MB-231) are markedly increased when targeting both EZH2 and EHMT2, either by siRNA knockdown or pharmacological inhibition, rather than either enzyme independently." (PMID 26300989, 2015). "We tested the impact of EHMT2 knockdown in triple-negative breast cancer (TNBC) cells, a cancer type that is not very responsive to adaptive immune checkpoint blockade therapies (anti-PD-1, anti-CTLA4, etc.)." (PMID 41366520, 2026).
Type 2 diabetes (3 papers, 2020 to 2023). "Two loci, EHMT2 (lead SNP rs1265945) and lincRNA RP1-230L10.1 (lead SNP rs66930764), shared by type 2 diabetes and chronotype, were duplicated in FI." (PMID 35203577, 2022).
acute promyelocytic leukemia (2 papers, 2019 to 2023). An aggressive form of acute myeloid leukemia (AML), characterized by arrest of leukocyte differentiation at the promyelocyte stage, due to a specific chromosomal translocation t(15;17) in myeloid cells. "EGCG treatment has been demonstrated to decrease DNMT1 levels, as well as euchromatic histone lysine methyltransferase 2 (G9a), HDAC1/2 and polycomb repressive complex 2 (PRC2) in acute promyelocytic leukemia cells." (PMID 37513933, 2023).
Aortic dissection (2 papers, 2020 to 2023). Aortic dissection refers to a tear in the intimal layer of the aorta causing a separation between the intima and the medial layers of the aorta. "Overall, these findings suggest that EHMT2 functions as a crucial negative regulator of ACD via decreasing SQSTM1 or BECN1 expression and that EHMT2 could be a potent therapeutic target for cardiovascular diseases (e.g., aortic dissection)." (PMID 32174799, 2020). "Our data preliminarily showed that pharmacologic manipulation of EHMT2 could impact VSMC numbers and function and may be a potential treatment target for CVDs, such as aortic dissection." (PMID 32174799, 2020).
autism spectrum disorder (2 papers, 2021 to 2025). A spectrum of developmental disorders that includes autism, and Asperger syndrome. "Likewise, a recent study that investigated Ngn2-induced neuronal network behavior of 12 autism spectrum disorder patients revealed hyperactive neuronal networks specifically from a patient with CNTN5 and a CRISPR-Cas9-engineered line with an EHMT2 mutation." (PMID 34329594, 2021).
autoimmune disease (2 papers, 2021 to 2024). A disorder resulting from loss of function or tissue destruction of an organ or multiple organs, arising from humoral or cellular immune responses of the individual to their own tissue constituents. "Overall, our study not only presents novel insights but also holds significant biomedical relevance in the context of autoimmune diseases, chronic inflammation, and emerging therapeutic strategies involving Ehmt2." (PMID 38948355, 2024).
B-cell chronic lymphocytic leukemia (2 papers, 2015 to 2021). "Applying rvGWAS to a Chronic Lymphocytic Leukemia study we identified eight candidate predisposition genes, including EHMT2 and COPS7A." (PMID 33606672, 2021).
cerebral infarction (2 papers, 2021 to 2023). An ischemic condition of the brain, producing a persistent focal neurological deficit in the area of distribution of the cerebral arteries. "Importantly, EHMT2 was measured to be overexpressed in penumbra neurons and astrocytes after photothrombotic stroke (PTS), and the addition of EHMT2 inhibitor protected penumbra cells from apoptosis and reduced the volume of PTS-induced cerebral infarction." (PMID 37529171, 2023).
developmental delay (2 papers, 2021). "Embryos with zygotic, or maternal mutation in the Ehmt2 gene exhibit variable developmental delay." (PMID 34793451, 2021). "We found that EHMT2 plays an important role in reducing transcriptional variation of genes and repeat elements at the six-somite stage embryos, which is consistent with its role in reducing variation in developmental delay." (PMID 34793451, 2021).
diffuse large B-cell lymphoma (2 papers, 2021). "The EHMT2 inhibitor triggered the inhibition of human diffuse large B-cell lymphoma cell proliferation leading to G1 phase arrest and induced apoptosis via endogenous and exogenous apoptotic pathways." (PMID 34367251, 2021).